CFH (complement factor H)
Diseases named in the same sentence as CFH in open-access papers (continued):
Sharing a sentence is not in itself a finding about the gene and the disease.
Autoimmunity (6 papers, 2014 to 2022). The occurrence of an immune reaction against the organism's own cells or tissues. "It is important to note that similar to mice with CFH deficiency, sIgM−/− mice also develop high autoantibody titers and autoimmunity." (PMID 31354740, 2019). "miR-146a-mediated CFH deficits are conducive to excessive complement pathway activation associated with autoimmunity and a sustained inflammatory response." (PMID 29590637, 2018). "Systemic CFH deficits are conducive to excessive and pathogenic complement activation associated with increased complement activity in healthy host cells, autoimmunity, host tissue damage, and a sustained or chronic inflammatory response." (PMID 29590637, 2018). "In this study, we aimed to solve why a deficiency of one molecule (CFHR1) predisposes to autoimmunity against another, highly homologous molecule (CFH) in aHUS." (PMID 25659429, 2015). "Deficiencies in CFH are associated with increased risk of persistent inflammation and autoimmunity." (PMID 32175298, 2020). "miRNA-155 has been shown to be significantly increased in DS, and this causes a significant down-regulation of CFH mRNA which may partly explain the increased prevalence of chronic inflammation and autoimmunity in this population." (PMID 32175298, 2020). "However, it still remains unknown whether the protective effect of B cell deficiency in this model is indirectly linked to CFH deficiency or whether CFH has the capacity to attenuate autoimmunity by directly modulating B cell responsiveness." (PMID 31354740, 2019). "As a direct down regulator of the complement classical pathway, CFH is likely to be involved in fine-tuning and balancing the C1q-driven inflammatory processes in autoimmunity and infection." (PMID 36059501, 2022). "In accordance with this, our data provide a direct link between CFH and B-cell dependent autoimmunity, as we found that CFH controls splenic C3 cleavage and modulates BCR signaling, thus contributing to physiological B cell development." (PMID 31354740, 2019). "Our findings identify a previously undefined role for CFH in protecting from autoimmunity and chronic inflammation." (PMID 31354740, 2019). "Here, we demonstrate that CFH deficiency results in heightened BCR signaling which affects splenic B cell development and leads to B cell-dependent autoimmunity with increased levels of dsDNA autoantibodies." (PMID 31354740, 2019). "Our findings provide a novel role for CFH in directly calibrating B cell responsiveness and limiting autoimmunity." (PMID 31354740, 2019). "Taken together, our data indicate that CFH, through its function as a complement repressor, acts as a negative regulator of BCR signaling and limits autoimmunity." (PMID 31354740, 2019).
breast carcinoma (6 papers, 2011 to 2024). "According to COSMIC, the DNAH11 variant is associated with esophageal carcinoma, while CFH is linked to breast cancer." (PMID 38970307, 2024). "Increased CFH expression is also linked to larger tumor size, metastasis, and late stage tumors in breast cancer." (PMID 38389705, 2024). "The TNBC-specific methylation and mRNA expression patterns of the ATP1A1, ADH1C, and CFH genes were also significantly altered in the TCGA cohort, depending on the breast cancer subtype." (PMID 38730618, 2024).
hepatocellular carcinoma (6 papers, 2020 to 2024). A malignant tumor that arises from hepatocytes. "However, these two reports are in contrast with the observations that more than 50% of aged male CFH-deficient mice develop spontaneous liver carcinoma." (PMID 35860237, 2022). "Further, it inhibits hepatocellular carcinoma (HCC) tumorigenesis and metastasis driven by tumor extracellular vesicles overexpressing CFH." (PMID 38389705, 2024).
non-small cell lung carcinoma (6 papers, 2021 to 2025). A group of at least three distinct histological types of lung cancer, including non-small cell squamous cell carcinoma, adenocarcinoma, and large cell carcinoma. "It has also been reported that complement factor H is over expressed in non-small cell lung cancer, blocking complement action on cancer cells." (PMID 35366267, 2021). "The GT103 antibody (previously mAb7968), was derived from an anti-CFH autoantibody that is associated with an early stage, non-metastatic phenotype in non-small cell lung cancer (NSCLC)." (PMID 34133431, 2021). "CFH, a fluid phase and cell surface complement regulator, which also reduces CDC, was found in extracellular vesicles (EV) secreted by non-small cell lung carcinoma (NSCLC)." (PMID 35860237, 2022). "Interestingly, early-stage non-small cell lung cancer patients who do not develop metastasis or recurrence after surgical resection had autoantibodies against CFH." (PMID 38389705, 2024).
retinal disease (6 papers, 2014 to 2025). "The therapeutic potential of supplementation of complement factor H (FH), a key regulator of the complement cascade, is therefore particularly promising in the context of retinal diseases caused by complement activation." (PMID 38388518, 2024). "Apoptosis is also a characteristic hallmark of retinal diseases, so BBC3 and BCL2L13, RARA were investigated, as well as genes (EFEMP1, CFH) involved in the regulation of methylation sites." (PMID 36078063, 2022). "BBS9, MPP7, MED27, these three genes found here to interact with CFH have also been reported to be important for retinal disease." (PMID 24901472, 2014). "Importantly, emerging evidence from C3-deficient and Complement factor H (CFH)-variant mouse models suggests a functional link between AMD-associated genetic variants and alterations in the gut microbiota, reinforcing the role of systemic factors in modulating retinal disease." (PMID 41301489, 2025). "While three proteins in the RPE secretome, collagen type 2, alpha 1, and complement factor H (CFH), were identified to be involved in retinal disease, CFH was the only candidate predicted to be tyrosine-sulfated by the program Sulfinator." (PMID 25136834, 2014).
autoimmune disease (5 papers, 2015 to 2021). A disorder resulting from loss of function or tissue destruction of an organ or multiple organs, arising from humoral or cellular immune responses of the individual to their own tissue constituents. "As a key regulator of the alternative complement pathway, abnormalities of CFH have been associated with many autoimmune diseases, including aHUS, C3 nephropathy, and SLE." (PMID 25994214, 2015). "Autoimmune aHUS is an unusual autoimmune disease because it is associated with a deficiency of a protein (CFHR1) homologous to the autoantigen (CFH)." (PMID 25659429, 2015). "Abnormalities of CFH resulting in dysregulation of the alternative complement pathway have been involved in the pathogenesis of several autoimmune diseases, including atypical hemolytic uremic syndrome (aHUS) and C3 nephropathy." (PMID 25994214, 2015).
complement deficiencies (5 papers, 2020 to 2024). "The most frequent main genetic causes of complement deficiencies in children infected with SARS-CoV-2 were CFH (n = 3), SERPING1 (n = 3), and FCN3 (n = 2)." (PMID 37559153, 2023).
Obesity (5 papers, 2012 to 2025). Accumulation of substantial excess body fat. "In concrete, proteomic analysis revealed higher abundance of four complement system proteins—C3, C4b, C8, and CFH, in cats with obesity." (PMID 39795034, 2025). "Interestingly, the association of complement factors (C3 and CFH) with anthropometric traits may reflect the low level inflammation induced by higher body mass, both of which associate with obesity, cardiovascular diseases, and increased susceptibility to infections." (PMID 35264221, 2022).
Sepsis (5 papers, 2011 to 2025). Sepsis is defined as life-threatening organ dysfunction caused by a dysregulated host response to infection. "Li with co‐authors investigates the genetic relationship between CFH SNPs and susceptibility to sepsis caused by bacterial infections in Chinese Han populations." (PMID 37803932, 2023). "Still, complement overrepresentation is not completely explained by population stratification, as when African American children with severe sepsis are compared to African gnomAD participants, C3 c.443G > A and CFH c.2850G > T remained overrepresented." (PMID 34973142, 2022). "443G > A; p.Arg148Gln) and CFH (c.2850G > T; p.Gln950His) were both more common than expected in African American children with sepsis." (PMID 34973142, 2022). "Also, in a rat model of sepsis induced by cecal ligation and puncture, administration of AM and AM-binding protein (AMBP-1 also known as complement factor H) were shown to prevent against endothelial cell dysfunction and decreased endothelium-dependent vascular relaxation in thoracic aorta." (PMID 22582036, 2011).
type 2 diabetes (5 papers, 2008 to 2025). "Association analysis of genotypes and alleles of CFH c.2808G>T SNP with new-onset microalbuminuria in type 2 diabetic patients from BENEDICT phase A." (PMID 31428128, 2019). "In summary, this study first revealed that CFH and CFB polymorphisms are associated with the development of DR, as well as with delayed progression to DR in type 2 diabetes." (PMID 23864767, 2013). "Similarly, the CFH polymorphism p.Glu936Asp, which associates with lower factor H levels and predisposes to aHUS, predicts CVD and new onset albuminuria in patients with type 2 diabetes." (PMID 40309771, 2025).
uveitis (5 papers, 2012 to 2023). An inflammatory process affecting a part of or the entire uvea. "The frequency of carriers of G allele for CFH-rs800292 was significantly higher in uveitis patients than in controls (GG/AG versus AA; p=0.02, OR=2.74)." (PMID 22876110, 2012). "Of these, variants in CFH, CFB and CFI involved in the alternative complement pathway, were identified as genetic risk factors for uveitis and specific subtypes." (PMID 28408754, 2017). "Nonetheless, these findings strengthen the concept that complement system especially CFH is involved in the development of uveitis." (PMID 22876110, 2012). "The exact mechanism is still unclear and further studies are required to investigate the functional interaction of CFH with uveitis." (PMID 22876110, 2012). "However, a higher expression of C3 and CFH proteins was observed in the aqueous humor, indicating that the inflammation seen in uveitis is a localized change in the anterior chamber of the eye and cannot be seen in the blood unless there is a blood-retinal barrier breakdown." (PMID 38187376, 2023). "A significant increase in the level of CFH in non-infectious uveitis as compared to that in infectious cases further confirmed the role of alternate complement pathway activation in NIU." (PMID 38187376, 2023). "The expression of C3 and CFH genes was significantly downregulated in the patients with non-infectious uveitis as compared to controls (C3, AAU vs. controls, FC -5.0 ± 0.7; *p = 0.03; CFH AAU vs. controls, FC -6.67 ± 1.0; *p = 0.04)." (PMID 38187376, 2023). "Multiplex ELISA was performed to measure alternative pathway complement components, such as C3b, factor B, and CFH, and aqueous humor of infectious and non-infectious uveitis patients and non-inflammatory controls (n=10 each)." (PMID 38187376, 2023). "Western blotting further validated (VitH) the activation of the complement cascade in the aqueous (AH) and vitreous humor of patients with non-infectious uveitis, with an increased level of C3b (n=6) and CFH (n=4) in aqueous humor." (PMID 38187376, 2023). "ELISA levels of C3b and CFH proteins were significantly higher in aqueous humor of infectious and non-infectious uveitis (*p = 0.03 and **p = 0.0007 respectively) as compared to the control group." (PMID 38187376, 2023).
viral infections (5 papers, 2020 to 2025). "Further, patients deficient in complement regulatory proteins, such as factor H (CFH) and factor B (CFB), are predisposed to bacterial and viral infections." (PMID 35764881, 2022).
age (4 papers, 2011 to 2025). A temporal measurement of the time period elapsed since an identifiable point in the life cycle of an organism. "Most reported data concern polymorphisms in the complement factor H and age-related maculopathy susceptibility 2 genes." (PMID 22046503, 2011). "Moreover, Locityper (LOO) achieves significant QV improvement (12.2) at the CFH gene, associated with age-related vision loss and kidney disorders." (PMID 39990346, 2025).
anterior uveitis (4 papers, 2011 to 2023). Inflammation of the iris and anterior chamber of the eye. "In addition, our previous study also demonstrated that CFH-rs800292 184G as a genetic risk marker for anterior uveitis in Chinese females." (PMID 22876110, 2012). "In contrast to our expectation, we noticed a downregulation of C3 and CFH expression in peripheral leukocytes of patients with anterior uveitis as compared to controls." (PMID 38187376, 2023).
bladder cancer (4 papers, 2002 to 2022). "This opposite behavior of aptamers binding C3–CH and CH only is consistent with a report that found higher levels of complement factor H in urine of bladder cancer patients." (PMID 36004048, 2022). "BTA STAT and BTA TRAK (Polymedco, Cortlandt Manor, NY, USA) are FDA-approved tests for the detection of complement factor H and related proteins in voided urine and it is used for bladder cancer follow up in addition to cystoscopy." (PMID 30544619, 2018). "Expression of CFH help in immune escape and it has been documented in malignant ovarian and bladder cancers." (PMID 30100996, 2018).
C3 glomerulonephritis (4 papers, 2016 to 2019). "For example, double knockout of complement factor H (CFH) and factor P (CFP) unexpectedly converts mild C3 glomerulonephritis to lethal C3 glomerulonephritis in mice." (PMID 31604923, 2019). "CFH plays a regulatory role in the alternative complement pathway and its dysfunction may lead to many renal diseases, such as HUS and C3 glomerulonephritis." (PMID 27460033, 2016).
central serous chorioretinopathy (4 papers, 2017 to 2022). "al. reported a genome-wide association study that revealed CFH rs800292 to be related with choroidal thickness in central serous chorioretinopathy (CSC) patients." (PMID 30596689, 2018). "Pregestational conditions like pituitary adenoma or genetic pedigree for complement factor H gene (1q31.1) single nucleotide mutations could lead to central serous chorioretinopathy or retinal detachment with severe, ischemic, central cilioretinal artery or vein occlusion and optic nerve atrophy." (PMID 29450378, 2017).
diabetic retinopathy (4 papers, 2017 to 2023). "Further, intense staining of complement proteins in the retinal tissues of diabetic donors with early vascular/DR changes as compared to control non-diabetic donor retina confirmed the role of CFH and C3 in diabetic retinopathy." (PMID 32117292, 2020).
epilepsy (4 papers, 2021 to 2023). A brain disorder characterized by episodes of abnormally increased neuronal discharge resulting in transient episodes of sensory or motor neurological dysfunction, or psychic dysfunction. "Recent studies have suggested a possible link between mutations or dysregulation of CFH and epilepsy." (PMID 38192726, 2023). "In the refractory TLE rat model, miR-146a increased the epilepsy susceptibility by reducing complement factor H. Hence, epilepsy-induced reduction of miR-146a differential expression could decrease the occurrence of epilepsy." (PMID 35328484, 2022). "In the refractory temporal lobe epilepsy (TLE) rat model, miR-146a increased the epilepsy susceptibility by reducing complement factor H. Thus, reducing the differential expression of miR-146a induced by epilepsy might reduce the occurrence of epilepsy." (PMID 33776649, 2021). "Complement factor H and ceruloplasmin were only detected in epilepsy dogs, suggesting that neuroinflammation plays a role in epileptic seizures." (PMID 38192726, 2023). "The plasma proteomic pattern was identified, and five major proteins potentially involved in the pathogenesis of epilepsy and control of Aβ levels, including HP, α2-macroglobulin, ceruloplasmin, CFH, and gelsolin, were identified." (PMID 38192726, 2023). "The plasma proteomic pattern was assessed, and five major proteins potentially involved in the pathogenesis of epilepsy and elevated Aβ levels were identified: haptoglobin (HP), α2-macroglobulin, ceruloplasmin, complement factor H (CFH), and gelsolin." (PMID 38192726, 2023). "CFH and ceruloplasmin were only detected in the plasma of dogs with epilepsy, suggesting potential roles in neuroinflammation and seizures." (PMID 38192726, 2023). "The findings suggested that haptoglobin, ceruloplasmin, α2-macroglobulin, complement factor H, and gelsolin play roles in canine epilepsy and Aβ levels based on proteomic profiling." (PMID 38192726, 2023). "In the present study, CFH was only detected in the plasma of dogs with epilepsy." (PMID 38192726, 2023).
Insulin resistance (4 papers, 2019 to 2023). Increased resistance towards insulin, that is, diminished effectiveness of insulin in reducing blood glucose levels. "Among these, CFH has been implicated in insulin resistance, as well as pathophysiology of various inflammation-mediated diseases." (PMID 38034020, 2023). "Second, the lack of data reflecting islet β cell function such as fasting insulin and C-peptide levels resulted in the defect of the putative association between CFH and insulin resistance during pregnancy." (PMID 34404360, 2021). "Notably, the lean NAFLD group exhibited significantly elevated levels of plasma CFH, which has been implicated in insulin resistance and the pathophysiology of various inflammation-mediated diseases." (PMID 38034020, 2023). "Complement factor H (CFH) has been found to be associated with insulin resistance." (PMID 34404360, 2021). "However, from our perspective, the co-occurred changes within the core of AFM, CP, and CFH were a secondary response to insulin resistance and might be caused by other dependent reasons." (PMID 33184417, 2020). "Furthermore, AFM, GSN, CFH, HGFAC, MMP2, and MMP9 have been previously associated with NAFLD or NAFLD-related factors such as liver damage, insulin resistance, metabolic syndromes, and extracellular homeostasis." (PMID 38034020, 2023). "Given that insulin resistance is an independent risk factor for NAFLD, it is not surprising that the lean NAFLD group exhibited significantly elevated levels of plasma CFH." (PMID 38034020, 2023).
major depressive disorder (4 papers, 2020 to 2023). An episode of depression lasting two or more weeks without an intervening episode of mania. "Our recent work indicated that increased plasma level of complement factor H (CFH) is associated with anhedonia in major depressive disorder." (PMID 37520223, 2023). "Our most recent work has shown that increased plasma level of CFH is associated with anhedonia in major depressive disorder (MDD)." (PMID 37520223, 2023). "In a recent study, increased levels of CFH in plasma were positively correlated with depression in geriatric patients." (PMID 32157596, 2020). "CFH/FHL-1 binding to MDA-modified bovine serum albumin (MDA-BSA) and CFH/FHL-1 concentrations were measured in plasma of 934 unrelated healthy individuals and of 896 unrelated patients with major depression disorder (MDD)." (PMID 32321835, 2020).
membranous nephropathy (4 papers, 2019 to 2024). "Additionally, there is also evidence of alternative pathway activation in primary membranous nephropathy as supported by genetic evidence for the deposition of PLA2R antibody, C3, and C5b-9 in patients with MBL deficiency and via production of antibodies targeting CFH." (PMID 38895123, 2024).